VIPR1 (vasoactive intestinal peptide receptor 1)
Diseases named in the same sentence as VIPR1 in open-access papers:
VIPR1 is named in the same sentence as 89 diseases in open-access papers, as found by Europe PMC text mining. Sharing a sentence is not in itself a finding about the gene and the disease. The quoted sentences say what the papers report.
breast carcinoma (11 papers, 2013 to 2024). "VIPR1 was found to be frequently overexpressed in a range of malignancies, such as gastric cancer, lung cancer, renal cancer, and breast cancer 13-16." (PMID 35864952, 2022). "LNCaP and C4-2 prostate cancer cell lines and MCF7 breast cancer cells expressed comparable levels of VIPR1." (PMID 28569785, 2017). "For example, some studies indicated that VIP/VIPR1 signaling stimulates transactivation of HER2 and EGFR in human breast cancer." (PMID 35864952, 2022).
colitis (8 papers, 2012 to 2022). Inflammation of the colon. "On the other hand, models of DSS-induced colitis in Vipr1-/- and Vipr2-/- mice displayed opposite results." (PMID 34322118, 2021). "In fact, Vipr1-/- mice showed a milder disease score compared to wild type mice, whereas Vipr2-/- developed a more severe colitis." (PMID 34322118, 2021).
lung carcinoma (5 papers, 2018 to 2022). "However, the expression of VIPR1 is lower in lung cancer tissues than in adjacent tissues, and overexpression of VIPR1 in lung cancer cells can inhibit cell proliferation, invasion, and migration." (PMID 36157238, 2022). "Vasoactive intestinal peptide receptor-1 (VIPR1) has a significant growth effect on many common tumors, and it is lowly expressed in human LUAD tissues and lung cancer cell line H1299." (PMID 33195408, 2020). "For other IRGs, such as LGR4, GDF10, GREM1, IL20RB, INHA, VIPR1, and ADM2, they had been verified to participate in carcinogenesis and affect patients’ prognoses in other cancers, although the relevant studies were rare in lung cancer." (PMID 33386920, 2021).
prostate carcinoma (5 papers, 2012 to 2020). A carcinoma that arises from epithelial cells of the prostate gland. "The clone, DUVIPR, that expressed physiological levels of VIPR1 (compared with other prostate cancer cells) was used throughout our experiments." (PMID 28569785, 2017). "In the same way as ADRB2, VIP receptors VIPR1 and VIPR2 are expressed in prostate cancer and engage PKA/pS75BAD mechanism to inhibit apoptosis in prostate cancer cells." (PMID 30871232, 2019).
asthma (4 papers, 2012 to 2024). "In response to asthma, sensory neurons release substance P. Administration of VIP into sensory neuron-depleted mice suppresses bacterial burden, while VIPR1 deficiency increases infection." (PMID 39414787, 2024). "The results confirmed that after stimulating the large intestine by Mangxiao or Dahuang, SP, NK1R, VIP, VIPR1, and VIPR2 were all significantly increased in large intestine tissue of rats with COPD and mice with asthma." (PMID 24023578, 2013).
gastric cancer (4 papers, 2019 to 2022). A primary or metastatic malignant neoplasm involving the stomach. "Ca2+ signaling is required for the carcinogenesis and progression of gastric cancer, and activation of VIPR1 by VIP can stimulate TRPV4-mediated Ca2+ entry." (PMID 36157238, 2022). "Functionally, elevated VIPR1 expression in gastric cancer promotes the malignant progression of gastric cancer by increasing the potential of gastric cancer cells to metastasis to distant regions." (PMID 36157238, 2022). "More intriguingly, in gastric cancer, VIPR1/TRPV4/Ca2+ signaling stimulates VIP secretion, enforcing a positive feedback loop in promoting cancer progression." (PMID 35864952, 2022).
hepatocellular carcinoma (4 papers, 2022). A malignant tumor that arises from hepatocytes. "In the current study, we investigated the role of the VIP/VIPR1 signaling in controlling hepatocellular carcinoma (HCC) progression." (PMID 35864952, 2022). "VIPR1 is also a hub gene that acts as a prognosis and progression biomarker for hepatocellular carcinoma." (PMID 35176017, 2022). "lncRNA-AC079061.1, hsa-miR-765, and VIPR1 were identified as independent factors that affect the prognosis of hepatocellular carcinoma." (PMID 36038907, 2022). "The present study identified the lncRNA-AC079061.1/VIPR1 axis as a novel biomarker that inhibited the proliferation and invasion of hepatocellular carcinoma, affecting the ultimate disease outcome." (PMID 36038907, 2022).
liver cancer (4 papers, 2020 to 2022). An epithelial or non-epithelial malignant neoplasm that arises from the liver. "This study showed that LUAD, KIRC and LIHC patients with low VIPR1 expression had poor prognosis, which was consistent with the findings in liver cancer and cervical cancer." (PMID 33195408, 2020). "Overall, VIPR1 gene can be used as a diagnostic feature marker of HCC and may be a potential target for the diagnosis and treatment of liver cancer in the future." (PMID 36157238, 2022). "Moreover, downregulation of Vipr1 mRNA and VIPR1 protein in HCC was also observed in a mouse model of diethylnitrosamine (DEN) -induced liver cancer." (PMID 35864952, 2022).
glioma (3 papers, 2017 to 2021). A benign or malignant brain and spinal cord tumor that arises from glial cells (astrocytes, oligodendrocytes, ependymal cells). "Of these 8 genes, 6 (SULT4A1, NDRG4, GAP43, BEX1, HINT1, LZTS1) are believed to act as tumor suppressants, while the remaining two, PKM and VIPR1, have been found to be overexpressed in glioma." (PMID 28957313, 2017).
colon cancer (2 papers, 2019 to 2022). "For example, VIPR1 was highly expressed in breast, gastric, and colon cancers, while it was significantly low expressed in lung, liver, and other cancers." (PMID 36157238, 2022). "It has been shown that the overexpression of VIPR1 in colon cancer may be related to the activation of EGFR, which can lead to poor differentiation of colon cancer, thereby promoting cancer progression." (PMID 36157238, 2022).
lung adenocarcinoma (2 papers, 2022). A carcinoma that arises from the lung and is characterized by the presence of malignant glandular epithelial cells. "It was worth noting that the expression of RXFP1, AVPR2, ADRB1 and VIPR1 had significantly effect on the survival of patients with lung adenocarcinoma." (PMID 36032660, 2022). "The researchers found that the overexpression of VIPR1 significantly inhibited the growth, migration, and invasion of in lung adenocarcinoma cells." (PMID 36032660, 2022).
ankylosing spondylitis (1 paper, 2018). An autoimmune chronic inflammatory disorder characterized by inflammation in the vertebral joints of the spine and sacroiliac joints. "Samples from ankylosing spondylitis patients were stained with a multimerized epitope from vasoactive intestinal polypeptide receptor 1 (VIPR1) presented by HLA B*27:05." (PMID 30008714, 2018).
bipolar disorder (1 paper, 2022). A disorder of the brain that causes unusual shifts in mood, energy, activity levels and the ability to carry out day-to-day tasks. "There is a single nucleotide polymorphism in VIPR1 that is associated with bipolar disorder." (PMID 35176017, 2022).
breast tumors (1 paper, 2017). "Our results confirm varying expression levels of VIPR1 in breast tumors." (PMID 28569785, 2017). "To confirm whether VIPR1 is also expressed in patient tumors, we compared VIPR1 mRNA expression in breast tumors and in tumor adjacent normal breast tissue by quantitative real-time PCR." (PMID 28569785, 2017). "Together, these results suggest that VIPR1 expression is maintained in breast tumors and might have a potential role in carcinogenesis." (PMID 28569785, 2017). "Furthermore, we isolated total protein from breast tumors and western blotted using VIPR1 antibody." (PMID 28569785, 2017).
clear renal cell carcinoma (1 paper, 2022). "In clear renal cell carcinoma (cRCC), some studies suggest that the proliferation-inhibitory role of VIP/VIPR1 signaling is related to the activation of EPAC/PI3K pathway." (PMID 35864952, 2022).
osteoporosis (1 paper, 2020). A condition of reduced bone mass, with decreased cortical thickness and a decrease in the number and size of the trabeculae of cancellous bone (but normal chemical composition), resulting in increased fracture incidence. "The neuropeptide VIPR1, finally, promotes bone mineralization, while TACR1 regulates the osteoblasts, osteoclasts and mesenchymal stem cell functionality associated with protection from osteoporosis." (PMID 32927845, 2020).
viral pneumonia (1 paper, 2025). Inflammation of the lung parenchyma that is caused by a viral infection. "Furthermore, we have elucidated that amygdalin functions as an exogenous ligand for VIPR1 activation, thereby providing mechanistic insights into its preventive and therapeutic actions against viral pneumonia from the perspective of neuroendocrine regulation." (PMID 41034926, 2025).
infection (37 papers, 2006 to 2025). The state of being infected such as from the introduction of a foreign agent such as serum, vaccine, antigenic substance or organism. "Furthermore, VIPR1–/– had an altered accumulation of select B cell populations, reduced immunoglobulins and cytokines, and increased bacterial burden in comparison to WT littermates in response to pre-exposure and infection." (PMID 39414787, 2024). "In addition, when neutrophils were ablated with a neutralizing antibody, VIPR1–/– mice did not further increase the bacterial burden in their lungs following pre-exposure and infection." (PMID 39414787, 2024).
tumor (30 papers, 2012 to 2026). "On the contrary, in the low-risk group, the expressions of IL3RA, CX3CR1, ARRB1, LIFR, and VIPR1 were higher than those in the high-risk group, which signified that they have a tumor suppressor effect." (PMID 35833114, 2022). "The results showed that the lower expression of VIPR1 was associated with the poor differentiation of tumor grade classification and malignant progression of clinical stage (P < 0.05)." (PMID 36157238, 2022). "Vasoactive Intestinal Peptide Receptor 1 (VIPR1) expression is significantly reduced in human HCC tissues and is associated with advanced clinical stages, tumor growth, recurrence, and poor patient outcomes." (PMID 39090094, 2024). "Next, we evaluated the clinical significance of tumor VIPR1 and serum urea levels by measuring VIPR1 expression of HCC tissue, serum urea, and AFP level in a cohort of 43 HCC patients." (PMID 35864952, 2022). "Our data showed that both mRNA and protein levels of VIPR1 were significantly downregulated in HCC tissues compared to the matched adjacent-non tumor tissues." (PMID 35864952, 2022). "The vasoactive intestinal peptide receptor-1 (VIPR1) has prominent growth effects on a number of common neoplasms." (PMID 36032660, 2022). "Our data revealed that loss of VIPR1 expression is associated with enhanced HCC growth, tumor grade and metastasis." (PMID 35864952, 2022). "In addition, VIP is released from tumor and immune cells, and it regulates immune reactions such as anti-inflammatory activities through interactions with VIPR1 and VIPR2." (PMID 37405999, 2023). "Similarly, spider plot analysis showed VIPR1 levels negatively correlated with the relapsed tumor size after surgery." (PMID 35864952, 2022). "In addition, by using multivariable Cox regression analysis, we found that advanced clinical stage was a hazard factor for tumor progression; however, VIPR1 mRNA expression level represented an independent predictor for better prognosis of HCC." (PMID 35864952, 2022). "Moreover, in 27 of 45 samples (60%), the VIPR1 expression was higher in tumor tissue than in normal tissue." (PMID 28569785, 2017). "Among the characteristic gene generated from the model, loss of VIPR1 expression in HCC facilitated CAD phosphorylation and tumor progression, suggesting that the restoration of VIPR1 and treatment with the VIPR1 agonist may represent a promising approach for HCC treatment." (PMID 38812780, 2024). "However, VIP/VIPR1 signaling has also been reported to inhibit tumor growth/proliferation." (PMID 35864952, 2022). "In addition, the overexpression of VIPR1 in tumor vessels and macrophages may play an important role in cancer invasion." (PMID 36157238, 2022). "VIPR1 overexpression significantly inhibited the proliferation and invasion of NSCLC cells, confirming its tumor-suppressive role." (PMID 42210336, 2026). "Approach and results: By analyzing clinical samples, we found the expression level of VIPR1 was downregulated in human HCC tissues, which was correlated with advanced clinical stages, tumor growth, recurrence, and poor outcomes of HCC clinically." (PMID 35864952, 2022). "First, it has been well defined that VIPR1 gene transcription is regulated by members of the nuclear receptor superfamily, including farnesoid X receptor (FXR) 9, a potent tumor suppressor of HCC that can directly repress oncogene transcription." (PMID 35864952, 2022). "To investigate the role of VIPR1 in regulating HCC progression, we first examined VIPR1 mRNA levels in 41 paired HCC and adjacent non-tumor tissues." (PMID 35864952, 2022). "The VIPR1 gene is downregulated at the level of LUAD cells and plays a key tumor suppressor role in the progression of LUAD." (PMID 35620271, 2022). "Our data revealed that VIPR1 mRNA expression was inversely correlated with aggressive features of HCC, including the size and number of tumor mass, vascular invasion, distant metastasis, and advanced TNM stage." (PMID 35864952, 2022).
tumor (continued). "It has been reported that daily subcutaneous administration of VIPhyb, an antagonist of both VIPR1 and VIPR2, induces anti-tumor effects against CT26 cells implanted to severe combined immunodeficient (SCID) mice and enhances the pharmacological effects of an anti-PD-1 antibody." (PMID 37405999, 2023). "To further analyze the potential effect of VIPR1 on tumor pathological characteristics, we performed univariable analysis in an HCC cohort of 107 post-surgical-patients to determine the differences between high- and low- VIPR1-expressed patient subgroups." (PMID 35864952, 2022). "To investigate whether VIP can elicit anti-tumor effects in vivo, we established HCC xenograft mouse models by subcutaneously implanting VIPR1 overexpressing HCCLM3 cells (HCCLM3-VIPR1) or vector transduced with HCCLM3 cells (HCCLM3-Vector) in the back of nude mice." (PMID 35864952, 2022). "Furthermore, analysis of TCGA-LIHC cohort also revealed that VIPR1 expression was significantly downregulated in HCC tissues compared to normal liver tissues, and its expression levels negatively correlated with tumor grade." (PMID 35864952, 2022). "VIP/VIPR1 signaling maintained tumor proliferation and invasiveness by upregulating the expression of cyclins and angiogenic factors, including cyclin D1, MMP-2/MMP-9, VEGF, and COX-2, as well as stimulating tumor growth through the activation of PKA/ERK1/2 pathway." (PMID 35864952, 2022).
cancer (23 papers, 2013 to 2026). A tumor composed of atypical neoplastic, often pleomorphic cells that invade other tissues. "GSEA of TCGA LUAD transcriptome data showed that pathways related to cell cycle, gene expression, metabolism, DNA damage, and cancer were more significantly enriched in low expressing VIPR1 patient group." (PMID 38095636, 2023). "According to the findings of earlier research, VIPR1 has been found to have a variety of expressions and functions, depending on the specific type of malignant tumor." (PMID 36157238, 2022). "By utilizing the GDSC and CTRP databases, we obtained the correlation between VIPR1 expression and drug sensitivity in pan-cancer." (PMID 36038907, 2022). "A further cancer-related gene with rhythmic AS, based on our results, is VIPR1 (Vasoactive Intestinal Peptide Receptor 1 gene, p = 9.71E-05, Supp." (PMID 31363108, 2019). "Additionally, VIPR1 and VIP/VIPR1 signaling have received great attention in cancer research because of their pleiotropic roles in different types of cancer." (PMID 35864952, 2022). "VIP-immunoreactivity occurs in a number of tumors, and VIPR1 is overexpressed, resulting in high densities, in numerous cancers including bladder, breast, colon, lung, pancreatic, and prostate cancers, although there are some inconsistencies with other studies." (PMID 36237322, 2022). "We first determined the expression levels of VIPR1 in various cancer cells." (PMID 28569785, 2017). "VIPR1 (vasoactive intestinal polypeptide receptor 1, or VPAC1) is consistently downregulated across all cancer to normal sample comparisons." (PMID 31480259, 2019). "A recent study comprehensively investigated the cytoprotective effects of the small neuropeptide VIP and its receptor (VIPR1) in cancer stem cells and identified an antiapoptotic function of the VIP receptor in these cancer cells." (PMID 31363108, 2019).
bacterial infection (1 paper, 2022). "In this study, the VIP precursor gene (On-VIP) and its receptor gene VIPR1 (On-VIPR1) were identified from Nile tilapia (Oreochromis niloticus), and the functions of On-VIP in the immunomodulation of Nile tilapia against bacterial infection were investigated and characterized." (PMID 36499231, 2022).
VIPR1 also shares sentences with these, for which no sentence is quoted: migraine (13 papers); Arthritis (6); shigellosis (5); glioblastoma (4); rheumatoid arthritis (4); autoimmune disease (3); Headache (3); immune disease (3); leukemia (3); melanoma (3); metabolic syndrome (3); multiple sclerosis (3); adenocarcinoma (2); allergic asthma (2); atherosclerosis (2); Autoimmunity (2); bladder cancer (2); cognitive decline (2); colorectal cancer (2); COVID-19 (2); diabetes (2); endotoxemia (2); experimental autoimmune encephalomyelitis (2); Hypoglycemia (2); inflammatory bowel disease (2); neurodegenerative disease (2); Obesity (2); pancreatic cancers (2); schizophrenia (2); Achalasia (1).
A further 38 diseases each share a sentence with VIPR1 in 1 paper.